ROCK1 (Rho associated coiled-coil containing protein kinase 1)
Diseases named in the same sentence as ROCK1 in open-access papers (continued):
Sharing a sentence is not in itself a finding about the gene and the disease.
glioma (continued). "For instance, sevoflurane through regulation of circ_0079593/miR-633/ROCK1 axis could suppress tumorigenesis process in glioma." (PMID 36177350, 2022). "LINC00346 may also be able to regulate the expression of ROCK1 through miR‐145 or miR‐124, thus participating in the development of glioma." (PMID 32996285, 2020). "In addition, ROCK1 has been shown to be a novel target of miR‐145, thus promoting glioma cell invasion." (PMID 32996285, 2020). "In addition, we showed that ROCK1 levels were higher in glioma tissues than in normal brain tissue, and ROCK1 levels were significantly negatively correlated with miR‐340‐5p levels in glioma samples." (PMID 32996285, 2020). "Furthermore, we demonstrated that LINC00346 promotes glioma cell proliferation, migration, and invasion and inhibits apoptosis by increasing the output of the miR‐340‐5p‐ROCK1 axis." (PMID 32996285, 2020). "In addition, we showed that ROCK1 levels positively correlated with LINC00346 levels in glioma tissues." (PMID 32996285, 2020). "For example, miR-124 could inhibit the growth of glioblastoma by downregulating SOS1, radio-sensitizing human glioma cells by targeting CDK4, and suppressing the migration and invasion of glioma cells via Capn4 and ROCK1." (PMID 31052326, 2019). "In addition, the ROCK-1 protein levels were significantly decreased in miR-584-3p mimic-transfected U251 and U87 cells and were elevated in miR-584-3p inhibitor-transfected glioma cells, particularly under hypoxic conditions." (PMID 26715733, 2016). "To examine whether miR-584-3p expression is correlated with the ROCK-1 level in human glioma, we detected ROCK-1 expression in 26 human glioma specimens of different grades by immunohistochemical staining." (PMID 26715733, 2016). "A new study has reported knockdown of ROCK1 suppresses proliferation and invasion of glioma cells." (PMID 27557508, 2016). "U251 and U87 glioma cells were treated with Y-27632 and transfected with ROCK1 siRNA, respectively." (PMID 26715733, 2016). "Conversely, our study unveiled that ROCK1 inhibition reduced the self-renewal in glioma stem cells, which suggests the function of ROCK1 may differ in different cancer stem cells." (PMID 27557508, 2016). "On the other hand, other target molecules might help miR-584-3p to inhibit glioma cell migration and ROCK1 expression." (PMID 26715733, 2016). "In summary, our results demonstrate the anti-migratory and anti-invasive effects of a novel ROCK-1 inhibitory miRNA, miR-584-3p, and suggest that miR-584-3p may represent a prognostic biomarker of high-grade glioma." (PMID 26715733, 2016). "Furthermore, ROCK1 was validated as a direct functional target miR-340 in glioma and silencing of ROCK1 phenocopied the anti-tumor effect of mR-340." (PMID 25831237, 2015). "In addition, a significant inverse correlation between the levels of miR-340 and mRNA expression of ROCK1 was observed in glioma." (PMID 25831237, 2015). "In addition, ROCK1 is found to be highly expressed in glioma and correlated with the degree of malignancy of astrocytic tumors." (PMID 25831237, 2015). "Knockdown of ROCK1 expression dramatically suppressed proliferation and migration of glioma cells." (PMID 25831237, 2015). "We specifically suppressed expression of ROCK1 in glioma cells using siRNA targeting ROCK1 mRNA." (PMID 25831237, 2015). "Thus, designing an inhibitor that specifically blocks ROCK1 and using a siRNA approach would further help to unravel its role in primary gliomas." (PMID 23936026, 2013). "Based on the inhibitory effects of miR-124 on ROCK1 protein expression and glioma cell locomotion, we reasoned that miR-124 may have an impact on cell invasive capacity." (PMID 23936026, 2013). "Moreover, a constitutively active ROCK1 in miR-124 over-expressed glioma cells reversed the effects of miR-124." (PMID 23936026, 2013).
glioma (continued). "Notably, a constitutively active ROCK1 in miR-124 over-expressed glioma cells reversed the effects of miR-124, suggesting the biological role of preventive invasion of miR-124 due mainly to the ROCK1 down-regulation." (PMID 23936026, 2013). "Nine novel functional miRNAs (hsa-miR-129, -136, -145, -155, -181b, -342-5p, -342-3p, -376a/b) in GBM cell lines were validated for their importance in glioma cell growth, and similar effects for six target genes (ROCK1, RHOA, MET, CSF1R, EIF2AK1, FGF7) of these miRNAs were shown functionally." (PMID 23577178, 2013). "Moreover, a constitutively active ROCK1 in miR-124 over-expressed glioma cells rescued the effects of miR-124." (PMID 23936026, 2013). "Propofol inhibited glioma cell proliferation, migration, and invasion by regulating the miR-410-3p/transforming growth factor-B receptor type 2 (TGFBR2) axis, the miR-206/Rho-associated protein kinase 1 (ROCK1) axis, and miR-134 expression, as well as suppressing the PI3K/Akt signaling pathway." (PMID 38786726, 2024). "Moreover, the oncogenic role of LINC00346 in glioma may be partly explained by the inactivation of miR‐340‐5p and thus, the disinhibition of ROCK1 expression." (PMID 32996285, 2020). "Moreover, to clarify whether ROCK1 was involved in the tumour‐suppressive effects of miR‐340‐5p in glioma cells, transfection combinations were performed prior to the assessment of glioma cell proliferation, migration, invasion and apoptosis." (PMID 32996285, 2020). "Our present findings have shown that ROCK-1 is a miR-584-3p target gene and that miR-584-3p expression is correlated with the survival prognosis of glioma patients, suggesting that miR-584-3p may be involved in glioma progression." (PMID 26715733, 2016). "Moreover, miRNA-124 might inhibit glioma cell migration and invasion by targeting ROCK1 gene and impairing actin cytoskeleton rearrangements and reducing cell surface ruffle." (PMID 27815936, 2016). "In the present study, we investigated whether the shRNA-induced inhibition of either ROCK1 or ROCK2 alone influences glioma migration and proliferation and elucidated the differences between these two ROCKs in glioblastoma cell migration, substrate preferences, and cell proliferation." (PMID 24170433, 2014). "Recently, ROCK1 is found as a novel Rac1 effector, and TRPV4 targets the AKT for phosphorylation, promotes migration and invasion through AKT/Rac1 signaling in glioma." (PMID 37369706, 2023). "LINC00346 promotes cell migration, proliferation, and apoptosis by targeting ROCK1 and miR-128-3p/SZRD1 axis in glioma." (PMID 34950662, 2021). "Previous studies have demonstrated that RhoC phosphorylates AKT via activating ROCK1, and phosphorylation of AKT plays a critical role in the development of glioma." (PMID 31905344, 2020). "Here, we found that ROCK1 levels were negatively correlated with miR‐340‐5p levels, but were positively correlated with LINC00346 levels in glioma tissues." (PMID 32996285, 2020). "Dynamin-related protein 1 (Drp1) was reported to contribute to mitochondrial dynamic regulation and influence glioma cells proliferation and invasion by RHOA/ ROCK1 pathway." (PMID 27852062, 2016). "We showed that miR-340 significantly decreased the luciferase activity of this construct to approximately 30% as compared with the control miRNA in U87 glioma cells, suggesting miR-340 was directly bound to the predictive sites located in 3′-UTR of ROCK1." (PMID 25831237, 2015). "ShRNA-mediated silencing of ROCK1 suppressed proliferation and motility, induced changes of morphology and up-regulation of GFAP, which phenocopied the effects of miR-340 on glioma." (PMID 25831237, 2015). "Using the glioma cell lines D54MG and 86HG39 treated with 100 μM Rho kinase inhibitor, nearly all tested proteins displayed the same regulation as in the cells with ROCK1 knockdown." (PMID 24170433, 2014).
glioma (continued). "This suggests the presence of a feedback loop of ROCK expression on RhoA since ROCK1 and ROCK2 are downstream effectors of RhoA in glioma cells." (PMID 24170433, 2014). "In contrast, ROCK1 was highly expressed and ROCK2 expression was almost undetectable in three WHO grade III and three WHO grade IV gliomas using immunohistochemistry and western blotting." (PMID 23936026, 2013). "In glioma, ILK promotes cancer cell migration and aggressiveness via activating ROCK1 and fascin-1." (PMID 35029589, 2022). "Knock-down of ROCK1 in glioma cells did not significantly influence EZH2, EGFR, XIAP and BMI1 expression, which indicates miR-340, regulates these oncogenes through distinct mechanisms bypassing ROCK1." (PMID 25831237, 2015). "Interestingly, miR-124 inhibited the migration and invasion of glioma cells through down-regulation of ROCK1, SOS1, CDK4, STAT3, and PPP1R13L expression, indicating miR-124 may be a valuable biomarker for glioma." (PMID 28060761, 2017). "However, the possible effect of ROCK1 on differentiation in glioma has, to our knowledge, never been investigated previously." (PMID 25831237, 2015).
lung cancer (37 papers, 2014 to 2026). A malignant neoplasm involving the lung. "It has been shown that ROCK-1 causes DNA breaks and cell cycle arrest via inhibiting the H2A.X/H2B-p21 axis, leading to irreversible DNA damage and apoptosis in lung cancer cells, thus favoring a promising target for the treatment of lung cancer." (PMID 39199381, 2024). "Rho‐associated protein kinase 1 (ROCK1) is a key serine/threonine kinase downstream of Ras homolog gene family, member A (RhoA), and the activation of RhoA/ROCK1 signaling can promote the invasion and migration in various cancer types, including lung cancer." (PMID 39023191, 2024). "Additionally, the Human Protein Atlas resource revealed high expression of BIRC5 or PLK1 to be associated with poor survival in renal, liver, and lung cancer patients and high expression of ROCK1 to be a marker of unfavorable prognosis in pancreatic cancer." (PMID 31523390, 2019). "Of note, miR-130a has been shown to be associated with chemotherapy response in ovarian cancer and lung cancer cell lines, while miR-1280 has recently been demonstrated to inhibit invasion and metastasis by targeting ROCK1 when over-expressed in bladder cancer." (PMID 24479446, 2014). "FECRs promote lung cancer malignancy metastasis and reduced response to chemotherapy through FECRs sequestration and subsequent inactivation of tumor suppressor miR-584-3p, leading to the activation of the Rho Associated Coiled-Coil Containing Protein Kinase 1 gene (ROCK1)." (PMID 34281588, 2021). "The expression levels of Cav-1, ROCK1 and Parkin in lung cancer cells treated with cisplatin are increased, and Cav-1 knockdown can inhibit ROCK1, downregulate Parkin related mitophagy." (PMID 41030451, 2025). "CAV1 knockdown enhances the therapeutic sensitivity of lung cancer to cisplatin-induced apoptosis by inhibiting parkin-related mitophagy and activating ROCK1 pathway." (PMID 40303344, 2025). "Both ATOX1 and ROCK1 were highly expressed and localized in the cytoplasm of Lewis lung cancer cells (LLCs), as confirmed by immunofluorescence." (PMID 40940984, 2025). "RhoA/ROCK1 signaling promotes cell migration, invasion, and metastasis in many cancer types, including lung cancer." (PMID 39023191, 2024). "In lung cancer, miR-26b inhibits the invasion and migration of cancer cells by directly targeting hENT1 depending on the RhoA/ROCK-1 signaling pathway." (PMID 35293283, 2022). "Mechanistically, cytoplasmic precursor CLU binds ROCK1 to decrease the phosphorylation of ERK1/2 by inhibiting the kinase activity of ROCK1, leading to an anti-metastatic effect in lung cancer cells." (PMID 35626071, 2022). "Cytoplasmic precursor CLU inhibits lung cancer metastasis by binding ROCK1 to decrease the phosphorylation of ERK1/2." (PMID 35626071, 2022). "In lung cancer, ROCK1 is involved in multiple pathologic processes, such as cancer cell proliferation, migration, and invasion, thereby promoting lung cancer tumorigenesis." (PMID 34271873, 2021). "Although a recent study demonstrated that ROCK1 is involved in lung cancer migration/invasion, the mechanisms by which ROCK1 impacts lung cancer survival are not fully understood." (PMID 32554853, 2020). "The aim of this study was to characterize the role of ROCK1 in lung cancer survival with a focus on the LATS2-JNK signaling pathway." (PMID 32554853, 2020). "A role for tumor cell proliferation and angiogenesis is also assumed based on the anti-proliferative and anti-angiogenic effects of ROCK1 inhibition in lung cancer cells." (PMID 31557128, 2019). "Multiple studies indicated that ROCK1 functions as an oncogene, and that ROCK1 over-expression promotes invasion and metastasis in lung cancer cells." (PMID 31638991, 2019). "In this study, we reported ROCK-1 activation, mediated by RNase L, resulting in the blebbing of phosphatidylserine in lung cancer cells and indicated this process as an essential mechanism in apoptosis." (PMID 31750234, 2019).
lung cancer (continued). "Our results provide detailed information on the molecular mechanisms by which hirsutine induces mitochondrial apoptosis in human lung cancer cells (i.e., by activation/cleavage of ROCK1, activation of PTEN, and inactivation of PI3K/Akt)." (PMID 29789524, 2018). "ROCK1 plays a crucial role in promoting epithelial-to-mesenchymal transition in lung cancer as well as invasion in gastric cancer." (PMID 25277193, 2014). "Proximity ligation assay (PLA) also detected the mutual interaction between CLU and ROCK1 in the cytoplasm of lung cancer cells, indicating that cytoplasmic CLU might function by regulating ROCK1." (PMID 35626071, 2022). "However, the regulation of the ROCK1 activity in lung cancer and the mechanism through which ROCK1 regulates lung cancer metastasis are not clearly understood." (PMID 35626071, 2022). "For example, circ_PIP5K1A via regulation of miR-493-5p/ROCK1 axis could regulate cisplatin resistance in lung cancer." (PMID 36177350, 2022). "Our findings suggest that cytoplasmic precursor CLU is capable of potently suppressing lung cancer progression by inhibiting the ROCK1/ERK axis, which might provide a potential anti-metastasis strategy for the treatment of metastatic lung cancer." (PMID 35626071, 2022). "Previous studies indicated that ROCK1 could promote the malignant development of lung cancer cells via PTEN/PI3K/FAK pathway." (PMID 34836544, 2021). "Our results showed that ROCK1 knockdown reduced A549 lung cancer cell viability in vitro." (PMID 32554853, 2020). "However, the precise mechanism by which ROCK1 regulates the phosphorylation states of PTEN/PI3K/Akt during hirsutine-mediated apoptosis in human lung cancer cells is unclear." (PMID 29789524, 2018). "To investigate whether miR-182/CTTN is involved in regulating Rac1 and ROCK by modulating invadopodia formation in lung cancer cells, we measured the protein levels of Rac1 and Rock1." (PMID 29986736, 2018). "Hence, the proposed G-Rh1 compound should be subjected to further experimental validation and may be used as a lead molecule for ROCK1 and RhoA inhibition and apoptosis regulation in treating and managing lung cancer." (PMID 36500403, 2022). "Moreover, G-Rh1 reduced the RhoA and ROCK1 gene expression in the A549 lung cancer cells." (PMID 36500403, 2022). "Moreover, KCNMB2-AS1 via sponging miR-374a-3p and regulating ROCK1 could assist in the progression of lung cancer." (PMID 36177350, 2022). "Therefore, RhoA/ROCK1 could be an ideal candidate target in lung cancer treatment as it is found to be highly expressed in cancer." (PMID 36500403, 2022). "Furthermore, our findings extend the current understanding of the kinase activity of ROCK1 without affecting cellular cytoskeleton and identify a novel mechanism underlying ROCK1-mediated ERK phosphorylation and activation due to CLU loss during lung cancer progression." (PMID 35626071, 2022). "Tumor-derived exosomes derived from lung cancer cells promote the invasion and migration of lung cancer cells by regulating the expression levels of specific genes, including those encoding the matrix metalloproteinases MMP-2, MMP-9, PTEN, E-cadherin, and ROCK1." (PMID 34511114, 2021). "This suggests that ROCK1 might also affect lung cancer development and progression." (PMID 32554853, 2020). "To validate this notion, we employed a traditional inhibitor of ROCK1, namely Y27632, in CLU-silenced lung cancer cells." (PMID 35626071, 2022). "Mechanistically, cytoplasmic precursor CLU binds ROCK1 to decrease phosphorylation of ERK1/2 by inhibiting the kinase activity of ROCK1, leading to an anti-metastatic effect in lung cancer cells." (PMID 35626071, 2022). "At the molecular level, the cytoplasmic precursor CLU binds ROCK1 to abrogate the interaction between ROCK1 and ERK and impair ERK activity, leading to the suppression of lung cancer metastasis." (PMID 35626071, 2022).
lung cancer (continued). "Inhibiting ROCK1 through Y27632 treatment significantly abrogated the pro-invasive and pro-migratory effects of silencing CLU in lung cancer cells." (PMID 35626071, 2022). "Collectively, these results suggest that CLU is able to bind ROCK1 to block the ROCK1/ERK axis and inactivates ERK1/2 activity, leading to the potent suppression of migration, invasion and metastasis in lung cancer." (PMID 35626071, 2022). "There are reports that BAP31 knockdown reduces expression level of TGF-β1, MMP-2, MMP-9, ROCK1, α-SMA, Vimentin and N-cadherin in cervical cancer, and BAP31 affects F-actin distribution to promote migration and invasion of lung cancer cells." (PMID 34179078, 2021). "RNase L activates the Caspase-3/ ROCK-1/PARP/ H2A.X+H2B/p21 axis and induces cell cycle arrest and apoptosis in lung cancer cells." (PMID 31750234, 2019). "In lung cancer, miR-148a targets MMP15 and ROCK1, resulting in reduced tumorigenesis and increased TRAIL dependent apoptosis." (PMID 28915601, 2017). "The cytoplasmic precursor of CLU binds to ROCK1, reducing the phosphorylation of ERK1/2 by suppressing the kinase activity of ROCK1 and thereby disrupting the connection between ROCK1 and ERK, therefore hindering ERK activity and reducing lung cancer’s ability to invade." (PMID 37685987, 2023). "Moreover, lung cancers (LUAD, LUSC) and tumors in the large intestine (COADREAD, READ, and COAD) also had a lower expression of ROCK1 than the normal tissues." (PMID 37683138, 2023). "Interestingly, the cytoplasmic precursor CLU binds ROCK1 to abrogate the interaction between ROCK1 and ERK and impair ERK activity, leading to the suppression of lung cancer invasiveness." (PMID 35626071, 2022). "Moreover, our current study reveals that cytoplasmic precursor CLU binds ROCK1 to abrogate the interaction between ROCK1 and ERK, leading to the suppression of lung cancer migration and invasion." (PMID 35626071, 2022). "In NSCLC, FPPS could induce TGF-β1-induced lung cancer cell invasion and EMT via RhoA/ROCK1 pathway." (PMID 31638991, 2019). "The present finding of RNase L activating ROCK-1 and inducing subsequent apoptosis provides further evidence of the specific function of ROCK-1 in cancer cells, thus indicating the crucial role of ROCK-1 activation in mediating apoptosis of lung cancer cells." (PMID 31750234, 2019). "In Lewis lung cancer cells (LLCs), ATOX1 and ROCK1 up-regulate each other in a negative feedback manner." (PMID 40940984, 2025). "However, the role of ROCK1 has not been fully explored in TGF-β1-induced EMT, especially in lung cancer." (PMID 31638991, 2019).